TNF (tumor necrosis factor)
Diseases named in the same sentence as TNF in open-access papers (continued):
Sharing a sentence is not in itself a finding about the gene and the disease.
anemia (continued). "Therefore, the increase in IFN-γ and TNF gene expression levels observed in these animals may negatively influence the differentiation of the erythroid lineage in bone marrow, aggravating the anemia presented by dogs with active L. infantum infections." (PMID 34442696, 2021). "Theoretically, this association between TNF-α and HbA1c might be useful clinically to follow up the level of glycemic control in patients with T2DM after medical treatment or changed lifestyle or in cases where HbA1c cannot be trusted due to defect in glycation or severe anemia." (PMID 32089876, 2020). "Second, although anemia-related parameters, such as iron, TSAT, and TNF-α, were significantly different at 12-week, the within-group differences were not significant for these parameters." (PMID 32994531, 2020). "For example, neutrophil invasion of the bone marrow produces TNFα, which perturbs RBC progenitor development, resulting in anemia." (PMID 33101313, 2020). "Of course, it is not enough to recognize and treat anemia as the guidelinesrecommend, but rather to act promptly in recognizing its cause, which asdemonstrated here may be disease activity due to failure or loss of response toanti-TNF." (PMID 33237166, 2020). "Of note, within the T. brucei infection model, this recovery was more pronounced in the IFN-γR−/−, CD8−/−, TNF-α−/−, and TNF-R2−/− mice, suggesting that a reduced early pro-inflammatory response/insult allows better recovery from acute anemia." (PMID 29497418, 2018). "Therefore, in IBD patients anti-TNF agents seem to play a role in ameliorating anaemia of chronic disease during a 6-week treatment; on the other hand, in a long-term treatment, anti-TNF therapy may also improve iron deficiency anaemia, throughout the induction of mucosal healing." (PMID 28191453, 2017). "Elevated levels of TNF and IFN-γ are related to severe forms of infection, such as cerebral malaria and severe anaemia in P. falciparum malaria." (PMID 26466783, 2015). "Anemia in patients with COPD is likely due to a combination of several factors: (i) Elevated cytokines levels, especially Tumor Necrosis Factor alpha (TNF α) and interleukin-6 (IL-6)." (PMID 24564844, 2014). "However, the mechanisms how anti-TNF-α inhibitors can improve RA-anemia is largely unknown." (PMID 24286116, 2013). "Furthermore, the fact that inhibition of NO production and neutralization of TNFα exacerbated lymphocyte loss rules out the possibility that NO production or TNFα signalling might contribute to leukopenia as they contribute to anaemia." (PMID 19478957, 2009). "In a cohort study in 2023, the proportion of patients receiving TNF-α treatment was 23% in the non-anemia group, while it was 16% in the anemia group." (PMID 39908327, 2025). "For example, it is known that inflammatory cytokines like interleukin-6 (IL-6) and tumor necrosis factor-alpha (TNF-alpha) may interfere with iron metabolism and erythropoiesis, leading to anemia of inflammation (AI) or anemia of chronic disease (ACD)." (PMID 39588439, 2024). "Blood gas analysis showed dilutional anemia during V-V ECMO, whereas plasma analysis revealed a decreased concentration of IL-10 during V-V ECMO therapy, and BAL measurements showed increased concentrations of TNF-α, CXCL2, and CXCL5." (PMID 38928327, 2024). "This study demonstrated that radiographic progression rates were increasing with the severity of anemia, and this effect was maintained in subgroups of patients treated with anti-TNF or corticosteroids, without non-selective NSAIDs." (PMID 37237405, 2023). "Altogether, these data suggest that the IL-6/hepcidin 1 axis and TNF-α are not involved in the anemia observed during CpG-induced MAS." (PMID 37074208, 2023). "It was observed from this analysis that the group of individuals with anemia had higher levels of IL-6, TNF- α, and IL-10 cytokines than the individuals without anemia (P < 0.05)." (PMID 35749690, 2022).
anemia (continued). "Cytokines IFN-γ and TNF-α were shown to be involved in exacerbation of anemia as mice lacking the respective genes exhibited protection from anemia, while anti-inflammatory cytokine, IL-10 counteracted the effects of Trypanosoma-induced anemia." (PMID 36504775, 2022). "The aim of this study was therefore to investigate the effect of moringa supplement on CD4+ count, tumor necrosis factor-alpha (TNF-α) level, and existing hematological abnormalities (anemia, leucopenia, lymphopenia and neutropenia) in HIV seropositive patients receiving HAARTs." (PMID 36407401, 2022). "The significance of TNF-α in our study group’s males, with a focus on males with anaemia since hospital admission, may point to TNF-α’s role in the pathogenesis of anaemia of inflammation." (PMID 36612220, 2022). "Alternatively, TNF-α and IL-1 have been shown to inhibit EPO production and therefore the inflammatory environment could suppress EPO production by the fetus during anemia." (PMID 33995348, 2021). "Similar to our previous report, we found that anemia-induced CECs did not suppress TNF-α production by CD11b+ cells in vitro." (PMID 34367164, 2021). "The increased cytokines (TNF-α, IFN-γ, IL-1 and IL-6) not only directly promote the development of RA, but also inhibit differentiation and proliferation of erythroid progenitor cells, result in the blunt response of erythropoietin to anaemia." (PMID 33198544, 2020). "The reason for the increased frequency of anemia in old age may be dysregulation of pro-inflammatory cytokines (CRP, TNF-α, IL-6 etc.)with aging." (PMID 31086504, 2019). "Using LT-α−/− mice, it was shown that the TIP sequence (i.e., lectin-like domain) of TNF-α does not seem to play a role in anemia development." (PMID 29497418, 2018). "Therefore, given the prevalence of anaemia and its impact on the quality of life in IBD, we studied prohepcidin levels and iron homeostasis and their potential modifications induced by anti-TNF treatment in a group of patients with IBD." (PMID 28191453, 2017). "Furthermore, we also observed that anemia was due to the decrease of DMT1 in inflamed mucosa, the latter was down-regulated by TNF but rescued by JNK inhibitor (JNK-IN-7)." (PMID 26572590, 2015). "The mean Hb increase was 1.4 g/dl in the tocilizumab group, which was significantly larger than that for the TNF-α inhibitor group (0.7 g/dl) (P < 0.01), indicating that tocilizumab had a more beneficial effect than TNF-α inhibitors on improvement of RA-anemia." (PMID 24286116, 2013). "Furthermore, both IL-6 and TNF-α can induce VEGF production and anemia reportedly impacts angiogenesis via impairment of tissue oxygenation, because hypoxia is a major stimulus for the up-regulation of VEGF." (PMID 24286116, 2013). "Human studies have specifically related elevated levels of TNF-alpha and IFN-gamma to dysfunction in the memory domain and other work in this cohort suggests that anemia of inflammation may be an important contributor to congnitive impairment." (PMID 22563514, 2012). "TNF-α, however, cannot be ruled out as a factor in the anaemia of cancer." (PMID 36612220, 2022). "Besides, tumor necrosis factor α (TNF-α) produced by macrophages also functions as a mediator of acute inflammation, platelet activation, and participation in the genesis of fever and anemia." (PMID 36159482, 2022). "We found statistically significant differences in hepcidin concentrations between non-anaemia men and men who developed anaemia when we compared hepcidin, IL-6, and TNF-α concentrations between non-anaemia and anaemia patients, as well as men who developed anaemia during their hospitalization." (PMID 36612220, 2022). "Although anemia-induced CECs did not suppress TNF-α production by myeloid cells in vitro, they may suppress innate immune response against B. pertussis in vivo." (PMID 34367164, 2021).
anemia (continued). "In addition, sick KD animals also showed myelofibrosis, higher numbers of white blood cells, platelets, and blast cells but no anemia and higher serum levels of TNF-α compared to KO mice and controls, indicating ongoing inflammation." (PMID 29925903, 2019). "In contrast, anemia in pristane-treated mice is dependent on TNFα and independent of IFN-I." (PMID 26097482, 2015). "The inflammatory response created by a subclinical or silent infection may lead to decreased responsiveness of bone marrow to erythropoietin mediated by inflammatory cytokines, specifically interleukin 1 (IL-1) and tumor necrosis factor alpha (TNF-α) and thus anemia." (PMID 24369448, 2013). "Moreover, the low ratio of total TNF-α to soluble TNF-R2 observed in BALB/c mice may account for the lack of TNF-mediated pathology, whereas an increased ratio in C57BL/6 mice coincided with the severe pathology/anemia." (PMID 29497418, 2018). "However, lower levels of a few key cytokines, such as TNF-α and IL-10, may be the key to controlling parasitemia without exacerbating anemia." (PMID 27418744, 2016). "In patients with anemia of chronic disease (ACD) who experience acute or chronic immune responses, the effect of TNF-alpha inhibitors has, however, been found to be independent of iron supplementation." (PMID 39518547, 2024). "IL-1 and TNF-α were shown to inhibit EPO mRNA, making anemia more common in TB due to inflammation rather than iron deficiency." (PMID 36106202, 2022). "In addition, blood levels of anemia-related inflammatory cytokines, including IFN-γ, TNF-α, IL-6 and IL-10, were not affected by the daily administration of 2500 mg TIMEx/kg body weight in both sexes." (PMID 34040996, 2021). "The observation that an inflammatory state compromises therapy of anemia in MDS patients is not new and could be also demonstrated for tumor necrosis factor-alpha and IL-1β in the context of ESA treatment." (PMID 33302451, 2020).
coronary artery disease (279 papers, 2006 to 2026). "First, chronic inflammation associated with coronary heart disease, driven by elevated cytokines such as interleukin-6 (IL-6) and tumor necrosis factor-alpha (TNF-α), accelerates bone resorption by activating osteoclasts." (PMID 40921881, 2025). "In patients with coronary artery disease, platelet activation is linked to elevated levels of inflammatory cytokines such as IL-1β, IL-6, and TNF-α." (PMID 40807011, 2025). "Specifically, CTRP2 expression has been shown to reduce oxidative stress, inhibit cytokine production such as TNF-α and IL-6 and has been linked to a number of inflammatory associated disease states (e.g., Coronary Artery Disease)." (PMID 40143094, 2025). "Knockdown of ENST00000416361 was found to significantly reduce levels of IL-6 and TNF-α, both of which are strongly associated with the progression of coronary artery disease (CAD)." (PMID 40941416, 2025). "The available literature has shown many works on the role of TNF-α polymorphisms and its receptors in coronary artery disease." (PMID 39684812, 2024). "At the same time, they indicated a significant association of the TNF-α 238G/A polymorphism with the incidence of coronary artery disease in the European and North Asian population." (PMID 39684812, 2024). "This is significant when considering that studies have shown correlative predictive effects for various conditions, such as coronary artery disease and infections associated with burn severities using TNFα/IL-10 ratios." (PMID 38435456, 2024). "Several proinflammatory cytokines, such as IL-6, IL-18, TNF-α and C-reactive protein, have been reported to be independently associated with the risk of coronary heart disease." (PMID 37308900, 2023). "In the case of the TNF-α gene, a pooled analysis revealed that carrying the TNF-α gene A variant conferred a 1.5-fold increased risk of developing coronary heart disease in the Caucasian population." (PMID 35893405, 2022). "In this regard, it has been shown that administration of L-carnitine at a dose of 1000 mg/d for 12 weeks in cases with coronary artery disease causes a significant reduction in the level of inflammatory biomarkers such as TNF-α and IL-6." (PMID 35936217, 2022). "Higher levels of interleukins (IL-6, -18) and tumor necrosis factor alpha (TNF-α) were also associated with development of coronary artery disease (CAD), cerebrovascular diseases and ACS, but their exact role is yet to be determined in larger clinical trials." (PMID 34207266, 2021). "The expression of proatherogenic inflammatory cytokine TNF-α was continuously increased in the patients with postinfarction and increased an elevated risk of recurrent coronary artery disease events." (PMID 33029103, 2020). "Recently published systematic review and meta-analysis have indicated an association between TNF-α G-308A gene polymorphism and the risk of ischemic heart disease." (PMID 30900134, 2020). "The goal of this study was to review relevant case-control studies to determine the association of tumor necrosis factor-α (TNF-α) gene polymorphisms and coronary artery disease (CAD) susceptibility." (PMID 32046680, 2020). "TNF-α inhibitors appeared to decrease the risk of ischemic heart disease yet increase the rate of cerebrovascular events." (PMID 30537997, 2018). "Positive associations were described for IL-18 and TNF-α only, with relative risks of coronary heart disease per 1-SD higher levels of 1.13 (95% CI 1.05–1.20) and 1.17 (1.09–1.25), respectively." (PMID 28477314, 2017). "A number of studies had reported the association between tumor necrosis factor-alpha (TNF-α) gene polymorphisms and ischemic heart disease (IHD) risk." (PMID 28383437, 2017). "For instance, human population studies have associated interleukin-6, C-reactive protein and TNF-α to age-related chronic diseases, like coronary heart disease and disability." (PMID 25888078, 2015).
coronary artery disease (continued). "We present a meta-analysis of independent studies on the potential implication in the occurrence of coronary heart disease (CHD) of the single-nucleotide polymorphism (SNP) at the −308 position of the tumor necrosis factor alpha (TNF-alpha) gene." (PMID 26401451, 2015). "Individuals with increased risk for coronary artery disease presented reduced interleukin-1 (IL-1), IL-6, TNF-α, and C-reactive levels, together with improved IL-10 and transforming growth factor beta-1 systemic levels after an ET program." (PMID 25045207, 2014). "At present, several protein and enzyme biomarkers are used for the identification of patients with risk of coronary diseases such as reactive C-protein, tumor necrosis factor α (TNF-α), receptors types 1 and 2 (sTNF-R1 and sTNF-R2), and interleukin-6." (PMID 23986911, 2013). "Several studies have established that CRP serum levels and other inflammatory markers (cytokines such as IL-1, IL-6, and TNF-α) are risk factors for coronary disease, although their levels are elevated in both coronary disease and chronic infections." (PMID 28348657, 2011). "Testosterone replacement therapy has also been shown to reduce circulating levels of inflammatory mediators, such as TNF-α and IL-1β as well as total cholesterol in patients with established coronary artery disease (CAD) and testosterone deficiency." (PMID 17137495, 2006). "Testosterone therapy has also been shown to reduce circulating levels of inflammatory markers, (TNF-α, sICAM-1 and sVCAM-1) in patients with established coronary artery disease and testosterone deficiency." (PMID 17137495, 2006). "In addition, it was noted that excessive levels of TNF-α in coronary heart disease are associated with increased uptake of modified LDL by macrophages, with a characteristic increase in the expression of scavenger receptors." (PMID 37047399, 2023). "Others revealed that serum MCP-1 levels were associated with coronary artery disease, as measured by the coronary artery calcium score, and increased plasma levels of IL-6 and TNF-alpha were associated with left ventricular diastolic dysfunction in patients with stable coronary artery disease." (PMID 37892788, 2023). "TNF-α is associated with increased risk of coronary heart disease development." (PMID 37534280, 2023). "In addition, Type D personality can activate the tumor necrosis factor alpha (TNF-alpha) and its receptors in patients with ischemic heart disease, causing the dysfunction of the human immune system." (PMID 35781348, 2022). "There may now be enough preliminary evidence from the crucial bundle neural network analysis to identify the risk of coronary heart disease associated with TNF pregeneration studies." (PMID 35813433, 2022). "Moreover, TNF-α is a proatherogenic agent and closely associated with prognosis in patients with coronary artery disease." (PMID 34199767, 2021). "Genetically predicted TNF levels were positively associated with coronary artery disease and IS." (PMID 34456968, 2021). "Also, Pai and colleagues examined the plasma levels of IL-6, CRP and tumor necrosis factor (TNF)-alpha as markers of risk for coronary artery disease among people who were free of cardiovascular disease at baseline." (PMID 22708908, 2012). "Numerous risk factors related to coronary artery diseases (CAD) contribute to increases in circulating TNF-α concentrations, resulting in higher caspase expression." (PMID 26459935, 2015). "Furthermore, testosterone replacement therapy can reduce circulating levels of inflammatory mediators including tumor necrosis factor α (TNF-α) and interleukin (IL)-1β, as well as total cholesterol in patients with established simultaneous coronary artery disease and testosterone deficiency." (PMID 25110677, 2014). "Studies have reported a significant reduction in the risk of ischemic heart disease (IHD) in patients treated with 5-aminosalicylates, and a modest risk reduction in those receiving azathioprine or anti-TNF therapy." (PMID 41155452, 2025).